HIF1A (hypoxia inducible factor 1 subunit alpha)
Diseases named in the same sentence as HIF1A in open-access papers (continued):
Sharing a sentence is not in itself a finding about the gene and the disease.
skeletal dysplasia (4 papers, 2021 to 2025). Any Mendelian diseases that affects growth and development of the skeleton. "PHD2 was identified as the main regulator of the normal development of growth plate chondrocytes in the avascular environment, as it can inactivate HIF1α to avoid prolonged HIF1α-induced skeletal dysplasia." (PMID 36324306, 2022). "Some researchers have found that prolonged HIF-1α signaling in chondrocytes leads to skeletal dysplasia by interfering with cellular bioenergetics and biosynthesis, reducing collagen synthesis, or causing excessive modification, which may also result in other ECM-related diseases, such as fibrosis." (PMID 40183102, 2025).
blood cancer (3 papers, 2018 to 2022). "VEGF and GLU1 are two target genes of HIF-1α; they intimately link to the growth and progression of solid and hematological tumors." (PMID 35528614, 2022).
colon (3 papers, 2008 to 2022). "However, to clarify to what extent HIF-1α expression level might be of prognostic significance in digestive system cancers, a comprehensive meta-analysis of previous studies is needed." (PMID 35845307, 2022).
mitochondrial disease (3 papers, 2021 to 2024). "Abnormal HIF-1α levels have also been reported in some primary genetic mitochondrial diseases." (PMID 39582684, 2024). "Abnormal HIF-1α levels have recently been reported in some primary genetic mitochondrial disease." (PMID 34285383, 2021). "It is possible that HIF1α expression is of importance in the large subgroup of mitochondrial diseases where the biogenesis of the whole OXPHOS system is impaired, whereas it may have no role in mitochondrial diseases caused by impaired stability of a single complex." (PMID 34779571, 2022).
peripheral neuropathy (3 papers, 2023 to 2025). A disorder affecting the peripheral nervous system. "Recently, the stabilization or overactivation of the HIF-1α signalling pathway, reflecting peripheral nerve hypoxia, has been similarly linked to the pathogenesis of both bortezomib- or paclitaxel-induced peripheral neuropathy." (PMID 39578077, 2025). "Only recently, it was reported that a loss of Hif1a in sensory neurons leads to a faster progression of peripheral neuropathy in diabetic mice." (PMID 37072781, 2023).
bone disorder (2 papers, 2014 to 2021). "To date, little is know about the association of HIF-1α polymorphism and bone disorders." (PMID 25401740, 2014). "Therefore, fully investigations into the effects of HIF-1α activation on bone micro-structure and remodeling are needed before clinically applying hypoxia-mimicking agents as treatments for skeletal diseases." (PMID 35118061, 2021).
central nervous system disorder (2 papers, 2017 to 2025). A disease involving the central nervous system. "Previous studies have suggested that hypoxia‐inducible factor 1‐α (HIF‐1α) exerted multiple effects on different central nervous system disorders." (PMID 40022282, 2025).
hematological cancers (2 papers, 2022 to 2023). "Collectively, our findings highlight the protective role of E2 on MDS by inhibiting hif1α-c-myb pathway, suggesting that E2 is a promising and effective drug for hematopoietic tumors associated with abnormal neutrophil hyperplasia." (PMID 35842445, 2022). "Contrary to HIF1-α, PRL-3 does not seem to reduce OXPHOS, and recent research has shown that many hematological cancers do not downregulate OXPHOS activity." (PMID 37361580, 2023).
musculoskeletal diseases (2 papers, 2012 to 2024). "Indeed, hypoxia is involved in the pathogenesis of several musculoskeletal diseases and is able to induce IGFBP-3 via HIF-1α in a wide range of cell cultures." (PMID 23036517, 2012).
connective tissue disease (1 paper, 2025). "We to measure the serum levels of hypoxia-inducible factor-1α (HIF-1α) and vascular endothelial growth factor (VEGF) in patients diagnosed with connective tissue disease (CTD)-associated pulmonary arterial hypertension (PAH) (CTD-PAH) and to analyze their clinical implications." (PMID 39948088, 2025).
endocrine tumours (1 paper, 2005). "The majority of endocrine tumours expressed high levels of cytoplasmic HIF-1α." (PMID 15558070, 2005).
gastrointestinal disease (1 paper, 2021). A disease that occurs in the gastrointestinal system, excluding the hepatobiliary system. "Different sources of ROS participate in the modulation of HIF-1α and further play a role in the pathologic progress of various gastrointestinal diseases." (PMID 33542787, 2021). "However, Clostridium difficile toxin-mediated ROS play a key role in the stabilization of HIF-1α, leading to the innate protection of colon epithelial barrier function, which suggested that HIF-1α played a dual role in gastrointestinal diseases." (PMID 33542787, 2021). "Overall, HIF-1α regulated by ROS plays a key role in gastrointestinal diseases." (PMID 33542787, 2021). "However, there were also studies that suggest that HIF-1α contributes to pathological progress in gastrointestinal diseases." (PMID 33542787, 2021). "As the crosstalk between HIF-1α and ROS plays a key role in gastrointestinal diseases, it might be a promising target for disease treatment." (PMID 33542787, 2021). "Moreover, the glutathione system is critical for the regulation of nonhypoxic HIF-1α in gastrointestinal diseases." (PMID 33542787, 2021).
myopathy (1 paper, 2019). A disease of the muscle in which the muscle fibers do not function properly. "The expression of HIF-1α at mRNA and protein levels was significantly induced in breasts (affected caudal area, WW and apparent healthy area, WN) of broilers with WB myopathy compared to their healthy counterparts, indicating a hypoxic status." (PMID 31632293, 2019).
psychiatric disorder (1 paper, 2023). A disorder characterized by behavioral and/or psychological abnormalities, often accompanied by physical symptoms. "Another protein that has been reported in multiple psychiatric disorders was HIF1A." (PMID 36746927, 2023).
reproductive system diseases (1 paper, 2024). "Interestingly, ALKBH5, a primary m6A demethylase, not only plays a key role in human reproductive system diseases, but is also believed to be directly regulated by HIF‐1α under hypoxia." (PMID 38344897, 2024).
HIF1A also shares sentences with these, for which no sentence is quoted: acute myocardial infarction (16 papers); skin cancer (7); anaplastic thyroid cancer (4); Allergy (3); arteriosclerosis (3); atrial fibrillation (3); cardiac arrhythmias (3); colon adenoma (3); malignant mesothelioma (3); nephritis (3); oropharynx carcinoma (3); placental insufficiency (3); prostatic hyperplasia (3); T Cell Lymphoma (3); amyotrophic lateral sclerosis (2); aortic atherosclerosis (2); astrocytic tumor (2); Barrett esophagus (2); bone cancer (2); breast invasive ductal carcinoma (2); cervical intraepithelial neoplasia (2); Chagas disease (2); cognitive disorder (2); endometrioid endometrial carcinoma (2); Erythema (2); essential hypertension (2); gastric disease (2); giant cell tumors of the bone (2); gliosarcoma (2); Graves disease (2).
A further 231 diseases each share a sentence with HIF1A in 2 papers or fewer.